EEF1A1 (eukaryotic translation elongation factor 1 alpha 1)
Diseases named in the same sentence as EEF1A1 in open-access papers (continued):
Sharing a sentence is not in itself a finding about the gene and the disease.
clear cell renal cell carcinoma (3 papers, 2018 to 2024). "SurvExpress analysis using TCGA-KIRC (Kidney clear cell carcinoma) dataset showed that higher expression levels of EEF1A1, EEF1G and EEF2 predicted better survival in low-risk group patients." (PMID 29342219, 2018). "For example, a high expression level of eEF1A1 was found to be a good prognostic factor in patients with colon adenocarcinoma, whereas a poor prognosis was found in patients with clear cell renal cell carcinoma and in diffuse large B cell lymphoma." (PMID 35456960, 2022). "As per TCGA analysis, expression levels of EEF1A1, EEF1B2, EEF1G, EEF1D and EEF2 were significantly upregulated in kidney clear cell carcinoma while that of EEF1E1 was downregulated." (PMID 29342219, 2018).
Hepatic steatosis (3 papers, 2015 to 2024). Steatosis is a term used to denote lipid accumulation within hepatocytes. "Previously, we demonstrated a role for eukaryotic elongation factor 1A1 (EEF1A1) in hepatocyte lipotoxicity, which is an initiating event in the progression from hepatic steatosis to MASH." (PMID 39136056, 2024). "eEF1A1 expression was found to be induced in HepG2 cells in response to palmitic acid as well as in obese mice with severe hepatic steatosis and ER stress." (PMID 27368608, 2016). "Our data from ob/ob mice show that liver eEF1A-1 protein is increased during severe hepatic steatosis, providing some evidence that this factor responds to conditions of hepatic lipotoxicity in vivo." (PMID 26102086, 2015). "We further found that liver eEF1A-1 protein was induced during severe hepatic steatosis and ER stress in obese ob/ob mice." (PMID 26102086, 2015). "Based on our bulk RNA-Seq analyses, we can speculate as to potential mechanisms through which inhibition of EEF1A1 with DB reduced hepatic steatosis." (PMID 39136056, 2024). "We also demonstrated that a 2-wk intervention with the EEF1A1 inhibitor didemnin B (DB) (50 μg/kg) decreased liver steatosis in a mouse model of obesity and metabolic dysfunction-associated steatotic liver disease (MASLD) [129S6/SvEvTac mice fed Western diet (42% fat) for 26 wk]." (PMID 39136056, 2024). "We previously demonstrated that inhibition of EEF1A1 with DB reduced hepatic steatosis in diet-induced obese mice with MASLD, and furthermore that DB decreased the proliferation and function in vitro of cell types that would contribute to liver inflammation and fibrosis." (PMID 39136056, 2024).
lymphoma (3 papers, 2015 to 2020). A malignant (clonal) proliferation of B- lymphocytes or T- lymphocytes which involves the lymph nodes, bone marrow and/or extranodal sites. "Interestingly, several genes that are frequently mutated in human lymphomas, such as Fas, Eef1a1 and some members of the histone family genes (Hist1h1b, Hist1h1d, Hist1h2bg, Hist1h3b) bear clonal variants (inset)." (PMID 33362210, 2020).
metastatic disease (3 papers, 2012 to 2022). "Similarly, metastatic breast cancers showed lower EEF1A1 expression than non-metastatic tumors." (PMID 30224719, 2018).
neuroblastoma (3 papers, 2014 to 2025). Neuroblastoma (NB) is the most common solid, extracranial childhood tumor. "Seven of our hits (Tubb1, Tubb5, Eef1a1, Eef1g, Gapdh, Nudc, Actg1) are present in their list of 52 enriched proteins from TGM2 stimulated N2a neuroblastoma cells." (PMID 41142754, 2025).
renal cell carcinoma (3 papers, 2020 to 2023). "Although high levels of EEF1A1 were reported in renal cell carcinoma, we found this gene to have the highest expression in NOR and one of the highest levels in PTC (68.47), albeit not significantly down-regulated." (PMID 32887258, 2020).
autoimmune disease (2 papers, 2023 to 2025). A disorder resulting from loss of function or tissue destruction of an organ or multiple organs, arising from humoral or cellular immune responses of the individual to their own tissue constituents. "This aligns with prior studies linking ubiquitination defects to autoimmune diseases, but our work uniquely identifies EEF1A1 as a SLE-specific driver." (PMID 41262540, 2025).
breast tumors (2 papers, 2005 to 2018). "EEF1A1 allelic copy number loss occurs in 27% of breast tumors, and this is significantly associated with reduced EEF1A1 mRNA expression compared to EEF1A1 diploid tumors (p < 0.0001, Mann-Whitney U test)." (PMID 30224719, 2018). "Also, comparison between breast tumor histological subtypes showed that EEF1A1 expression is significantly lower in ductal breast carcinoma than in lobular breast carcinoma (p < 0.0001, Mann-Whitney U test)." (PMID 30224719, 2018). "However, eEF1A1, the widely-expressed isoform, was recently shown to be upregulated in the infiltrating edge of invasive breast tumours compared with the tumour core by microarray analysis of laser microdissected material, confirmed by immunohistochemistry." (PMID 16156888, 2005). "We also observed decreased EEF1A1 levels in stage III tumors compared to stage I and stage II breast tumors (p < 0.01, Mann-Whitney U test)." (PMID 30224719, 2018).
chronic lymphocytic leukaemia (2 papers, 2022). "Recently, we have shown that the DNA aptamer GT75, which targets eEF1A1, can inhibit the viability of a panel of human HCCs and the chronic lymphocytic leukaemia cells." (PMID 35456960, 2022).
colon adenocarcinoma (2 papers, 2019 to 2022). "In conclusion, EEF1A1 may have a favorable prognostic effect on human colon adenocarcinoma, indicating that its loss can lead to poorer survival outcomes." (PMID 31703307, 2019). "The biological role of EEF1A1 in colon adenocarcinoma and its correlation with tumor sidedness will be evaluated in our next study." (PMID 31703307, 2019). "Based on the previous results from the Wx neural network-based feature selection algorithm and those reporting the role of EEF1A1 in human solid cancer, we hypothesized that EEF1A1 is related to the prognosis of patients with colon adenocarcinoma." (PMID 31703307, 2019). "However, the tumor suppressive role of EEF1A1 in colon adenocarcinoma remains unclear." (PMID 31703307, 2019). "EEF1A1 expression has been determined to be independent of KRAS mutations in our study, suggesting that the expression of EEF1A1 is unlikely to involve KRAS-related colon adenocarcinoma." (PMID 31703307, 2019).
ductal breast carcinoma (2 papers, 2018). "Taken together, we observe contradictory mRNA and protein misexpression of EEF1A1 in ductal breast carcinoma." (PMID 30224719, 2018). "EEF1A1 was found to be significantly downregulated in ductal breast carcinoma, compared to normal tissues, in Radyanvi and Richardson datasets." (PMID 29342219, 2018).
esophageal cancer (2 papers, 2023 to 2025). A primary or metastatic malignant neoplasm involving the esophagus. "In esophageal cancer, TOPK enhances the YB1/eEF1A1 signaling pathway, facilitating tumor growth both in vitro and in vivo." (PMID 40826334, 2025).
invasive breast carcinoma (2 papers, 2018 to 2021). A carcinoma that infiltrates the breast parenchyma. "Further, multiple datasets including Karnoub, Ma, Zhao and Finak, indicated that EEF1A1 was significantly downregulated in invasive breast carcinomas." (PMID 29342219, 2018).
ischemic stroke (2 papers, 2021 to 2025). A stroke disorder caused by obstruction of blood flow to the brain, due to thrombotic (local blood clot formation) or embolic (due to a blood clot or other material traveling from another site) event. "Our current study revealed a novel pharmacological mechanism of MLIF that protects against ischemic stroke via modulating microglia polarization by targeting eEF1A1." (PMID 34557098, 2021). "Taken together, our results demonstrated MLIF modulated microglia/macrophage polarization by targeting eEF1A1 in ischemic stroke." (PMID 34557098, 2021). "Thus, we speculated that eEF1A1 may exert an important effect in regulating microglia polarization in ischemic stroke." (PMID 34557098, 2021). "It was reported that HSC70 or eEF1A1 knockdown increases phosphorylated JNK, phosphorylation of c‐JUN, cleaved caspase‐9, and cleaved caspase‐3 expression in the background of ischemic stroke, which could be rescued by SP600125." (PMID 39764606, 2025).
lobular breast carcinoma (2 papers, 2018). "Transcript levels of EEF1A1 were also significantly reduced in lobular breast carcinoma, in Zhao dataset." (PMID 29342219, 2018).
lung adenocarcinoma (2 papers, 2018 to 2025). A carcinoma that arises from the lung and is characterized by the presence of malignant glandular epithelial cells. "Analysis in subtypes showed that EEF1A1 expression was reduced in lung adenocarcinoma, small cell carcinoma (both in Garber’s dataset) and squamous cell lung carcinoma (Hou’s dataset)." (PMID 29342219, 2018).
lung squamous-cell carcinoma (2 papers, 2016 to 2018). "For example, the eukaryotic translation elongation factor 1 alpha (eEF1A1) and inkel-Biskis-Reilly murine sarcoma virus (FBR-MuSV) ubiquitously expressed (FAU) genes have been newly developed as ideal reference genes for human lung squamous-cell carcinoma." (PMID 26891128, 2016).
metabolic dysfunction-associated steatotic liver disease (2 papers, 2015 to 2024). Metabolic dysfunction-associated steatotic liver disease (MASLD, formerly known as nonalcoholic fatty liver disease or NAFLD) is a type of liver disease that is not caused by alcohol. "Since ER stress is implicated in the pathogenesis of nonalcoholic fatty liver disease (NAFLD), we investigated the mechanism of action of eEF1A-1 in hepatocyte lipotoxicity." (PMID 26102086, 2015).
Obesity (2 papers, 2016). Accumulation of substantial excess body fat. "By contrast, our study confirms that RPL13A and EEF1A1 are stable reference genes for VAT or SAT samples from subjects with different degrees of obesity and IR." (PMID 27304673, 2016). "To determine whether chemical inhibition of EEF1A1 activity could improve hepatic lipotoxicity in a mouse model of obesity and metabolic syndrome, we used 5‐week‐old male C57BL/6J (lean control) and leptin‐deficient ob/ob mice." (PMID 27613825, 2016).
rheumatoid arthritis (2 papers, 2023 to 2025). A chronic, systemic autoimmune disorder characterized by inflammation in the synovial membranes and articular surfaces. "In the joints, synovial fibroblasts utilize EEF1A1 to accelerate the translation of IL-6 and IL-8, establishing a positive feedback loop of “translation-inflammation coupling” that promotes the progression of rheumatoid arthritis." (PMID 41262540, 2025).
skin cancer (2 papers, 2019 to 2023). "Studies have shown that 9-methoxycanthine-6-one affects the expression of EEF1A1, and 9-methoxycanthine-6-one is related to the activity of anticancer substances in vitro for skin cancer." (PMID 37663277, 2023).
Usher syndrome (2 papers, 2012 to 2019). A syndromic diseae characterized by the association of sensorineural deafness (usually congenital) with retinitis pigmentosa and progressive vision loss. "Several of the top candidate genes include EEF1A1, ROBO1, PLXNA4, SLIT3, NRP1, and NOTCH2, as well as genes associated with the Usher syndrome, PCDH15 and USH2A, and are plausible candidates contributing to the developmental defects in Gbx2−/− mice." (PMID 23144817, 2012).
acute myeloid leukemia (1 paper, 2024). Acute myeloid leukemia (AML) is a group of neoplasms arising from precursor cells committed to the myeloid cell-line differentiation. "In the TCGA dataset of acute myeloid leukemia (LAML), there was a significant decrease in EEF1A2 expression, while no significant decrease was observed in EEF1A1 compared with normal GTEx samples." (PMID 38172654, 2024).
asthenozoospermia (1 paper, 2017). "The exact cause of asthenozoospermia is unclear so far, and mutation of eEF1A1 might be lethal in mammals." (PMID 28266557, 2017). "Mutation of eEF1A1b in tilapia could be used as a model for investigating the possible involvement of eEF1A1 in asthenozoospermia." (PMID 28266557, 2017).
astrocytoma (1 paper, 2018). "In two datasets of Shai’s studies, EEF1A1 was significantly upregulated, in oligodendroglioma and astrocytoma." (PMID 29342219, 2018).
atherosclerosis (1 paper, 2025). A disease characterized by the build-up of fatty material and calcium deposition in the arterial wall resulting in partial or complete occlusion of the arterial lumen. "The eEF1A1/ARID3A/PKC‐δ complex critically regulates macrophage glycolytic reprogramming in atherosclerosis by mediating ARID3A phosphorylation and nuclear translocation, thereby driving ENO2 transcriptional activation." (PMID 39973763, 2025). "Neferine targets eEF1A1 to disrupt the eEF1A1/ARID3A/PKC‐δ complex to inhibit ENO2‐mediated macrophage glycolytic reprogramming in atherosclerosis." (PMID 39973763, 2025).
autism (1 paper, 2013). Persistent deficits in social interaction and communication and interaction as well as a markedly restricted repertoire of activity and interest as well as repetitive patterns of behavior. "Eukaryotic translation elongation factor 1 alpha 1-autism association, Thymosin beta 4 – provides neuroprotection following traumatic brain injury, LPP-homolog – reported to promote synapse development, and Rab-13 – promotes neurite growth and development." (PMID 24363837, 2013).
B cell lymphoma (1 paper, 2025). "In HCC and B cell lymphoma, overexpression of eEF1A1 predicts poor patient survival." (PMID 39962586, 2025).
bone cancer (1 paper, 2023). A primary or metastatic malignant neoplasm affecting the bone or articular cartilage. "As expected, miR-PC-2869 regulates the expression of CDK8, EEF1A1, and NTN1 in both human bone cancer and deer antler cells, suggesting that conserved target sites underlie the cross-species regulation of miR-PC-2869." (PMID 37446017, 2023). "Notably, cyclin-dependent kinase 8 (CDK8), eukaryotic translation elongation factor 1 alpha 1 (EEF1A1), and netrin 1 (NTN1), three functional targets of miR-PC-2869, jointly mediate the cellular functions of miR-PC-2869 in antler growth and bone cancers." (PMID 37446017, 2023).
brain ischemia (1 paper, 2022). Diminished or absent blood supply to the brain caused by obstruction (thrombosis or embolism) of an artery resulting in neurologic damage. "Our previous study has proved that MLIF can reduce the risk of brain ischemia injury by focusing on the eEF1A1/eNOS pathway." (PMID 36465453, 2022).
cardiac hypertrophy (1 paper, 2019). "By overexpression of TIP30 via AAV‐TIP30, the TIP30/eEF1A1 ratio was increased, which led to reduced cardiac hypertrophy and improved heart function after TAC." (PMID 31468715, 2019).
cardiomyopathy (1 paper, 2019). A disease of the heart muscle or myocardium proper. "To test whether elevation of the TIP30/eEF1A1 ratio could improve cardiomyopathy, we administered AAV‐TIP30 to mdx mice." (PMID 31468715, 2019). "Similar as in human cardiomyopathy, we found a strongly reduced myocardial abundance of TIP30 mRNA and protein and a markedly reduced TIP30/eEF1A1 ratio in the myocardium of 6‐month‐old mdx mice." (PMID 31468715, 2019).
cervical squamous cell carcinoma (1 paper, 2024). A squamous cell carcinoma arising from the cervical epithelium. "Interestingly, the TCGA dataset pertaining to cervical squamous cell carcinoma and endocervical adenocarcinoma (CESC) revealed no significant change in the expression of EEF1A2 but a decrease in EEF1A1 expression compared with normal tissue and GTEx normal samples." (PMID 38172654, 2024).
chondrosarcoma (1 paper, 2023). A malignant cartilaginous matrix-producing mesenchymal neoplasm arising from the bone and soft tissue. "To assess whether miR-PC-2869 exerts inhibitory effects on chondrosarcoma cells by downregulating CDK8, EEF1A1, and NTN1, we employed RNA interference to individually knock down the expression of each gene in SW1353 cells." (PMID 37446017, 2023).
dilated cardiomyopathy (1 paper, 2019). Cardiomyopathy which is characterized by dilation and contractile dysfunction of the left and right ventricles. "The TIP30/eEF1A1 ratio was strongly reduced in human failing hearts (with ischemic or dilated cardiomyopathy) as well as in human hearts from patients with hypertrophic cardiomyopathy." (PMID 31468715, 2019).
encephalitis (1 paper, 2017). An acute inflammatory process affecting the brain parenchyma. "For example, host eukaryotic translation elongation factor 1A1 (EEF1A1) can interact with NS3 and NS5 proteins of Japanese encephalitis (JEV) to form a complex that is essential for JEV replication, miR-33a can target EEF1A1 and reduce its expression, thus suppressing JEV replication." (PMID 29312306, 2017).
follicular lymphoma (1 paper, 2018). Follicular lymphoma is a form of non-Hodgkin lymphoma characterized by a proliferation of B cells whose nodular structure of follicular architecture is preserved. "However, Basso’s dataset for follicular lymphoma revealed upregulation of EEF1A1." (PMID 29342219, 2018).
gastric adenocarcinoma (1 paper, 2020). "AGS cells, a human gastric adenocarcinoma cell line, lacking eEF1A1 were infected with CagA+H." (PMID 32636937, 2020).
glioblastoma (1 paper, 2018). The most malignant astrocytic tumor (WHO grade IV). "Glioblastoma and glioma dataset revealed that EEF1A1, EEF1G, EEF1D and EEF2 were significantly overexpressed in tumor tissues whereas EEF1A2 was significantly downregulated." (PMID 29342219, 2018).
heart failure (1 paper, 2019). Inability of the heart to pump blood at an adequate rate to meet tissue metabolic requirements. "To analyze the TIP30/eEF1A1 ratio in human heart failure, we assessed myocardial mRNA levels of TIP30 and eEF1A1, because TIP30 protein could not be quantified in human samples due to the lack of a specific antibody." (PMID 31468715, 2019).
Hepatitis (1 paper, 2023). Inflammation of the liver. "Additionally, the involvement of EEF1A1 pseudogenes was observed in CHIKV and hepatitis E virus (HEV) infection." (PMID 36614310, 2023).
influenza (1 paper, 2023). An acute viral infection of the respiratory tract, occurring in isolated cases, in epidemics, or in pandemics; it is caused by serologically different strains of viruses (influenzaviruses) designated A, B, and C, has a 3-day incubation period, and usually lasts for 3 to 10 days. "It is possible that a similar mechanism might be associated with the six EEF1A1 pseudogenes identified in our study because for each of them higher expression was observed in influenza-infected cells." (PMID 36614310, 2023).
liver fibrosis (1 paper, 2016). "Future investigations in animal models of progressive NAFLD and liver fibrosis, and in the cell types involved in hepatic inflammation and fibrosis, will be critical for determining whether didemnin B, or inhibition of EEF1A1, will be effective in later stages of this disease." (PMID 27613825, 2016).
lupus (1 paper, 2025). "Although EEF1A1 is a ubiquitously expressed “housekeeping” protein, single-cell atlas data reveal its significant upregulation specifically in lupus renal monocytes and T cells, suggesting a disease-specific window of action." (PMID 41262540, 2025). "Given the high heterogeneity of SLE, the clinical utility of EEF1A1 as a serum biomarker requires further validation in prospective cohorts, particularly its correlation with SLEDAI scores and lupus nephritis flares." (PMID 41262540, 2025).
marginal zone B-Cell lymphoma (1 paper, 2018). "EEF1A1 was significantly downregulated in angioimmunoblastic T-Cell Lymphoma, centroblastic lymphoma and marginal zone B-Cell lymphoma subtypes, in Piccaloga’s, Bassos’s and Storz’s datasets, respectively." (PMID 29342219, 2018).
MELAS (1 paper, 2017). "Apart from many targets including PINK1, FOXO1, PPARγ and Apaf-1 investigated before, MKNK2, GREM1 and EEF1A1 that might be potential targets of miR-27b-3p were revealed in the regulatory network of MELAS pathogenesis." (PMID 28139706, 2017).